FOXM1 (forkhead box M1)
Description:
Transcription factor regulating the expression of cell cycle genes essential for DNA replication and mitosis. Plays a role in the control of cell proliferation. Also plays a role in DNA break repair, participating in the DNA damage checkpoint response. Promotes transcription of PHB2. [Isoform 5]: Required for the activation of Rho-associated protein kinases ROCK1 and ROCK2 and promotes epithelial-mesenchymal transition. Enhances the activation of phosphatidylinositol 4,5-bisphosphate 3-kinase (PI3K) by binding simultaneously to the catalytic and regulatory subunits. This relieves the inhibitory effect of the regulatory subunit on the kinase activity of the catalytic subunit, resulting in downstream signaling events such as AKT activation, GSK3B inactivation, and increased levels of SNAI1. Promotes glycolysis by binding to the pyruvate kinase PKM homotetramer to form a heterooctamer, inhibiting PKM activity. Promotes the IMP4-mediated nuclear translocation of both PKM and the NF-kappa-B complex which increases transcription of VEGFA, leading to increased angiogenesis.
Synonyms: HFH-11; FKHL16; HFH11; MPP2; trident; HNF-3; INS-1; MPHOSPH2; TGT3; FOXM1A; FOXM1B; FOXM1C; MPP-2; PIG29
Tractability: Small molecule: a high-quality ligand is known. PROTAC: UniProt records ubiquitination sites on it; ubiquitination databases record sites on it; a small molecule that binds it is known.
Target class: Transcription factor
Gene: Protein-coding gene on chromosome 12 (2,857,676 to 2,877,174, reverse strand). Ensembl gene ENSG00000111206.
Subcellular location: Nucleus (Isoform 1); Nucleus (Isoform 2); Cytoplasm (Isoform 4); Cytoplasm (Isoform 5)
Subcellular location (Human Protein Atlas): Nucleoli; Nucleoli rim; Nucleoplasm; Cytosol
Pathways (Reactome):
Cell Cycle: Cyclin A/B1/B2 associated events during G2/M transition; Polo-like kinase mediated events
Disease: Nuclear events stimulated by ALK signaling in cancer
Gene Ontology:
Molecular function: DNA-binding transcription factor activity; protein binding; protein kinase binding; RNA polymerase II transcription regulatory region sequence-specific DNA binding; DNA-binding transcription factor activity, RNA polymerase II-specific; DNA binding; sequence-specific DNA binding
Biological process: G2/M transition of mitotic cell cycle; negative regulation of DNA-templated transcription; negative regulation of stress-activated MAPK cascade; negative regulation of transcription by RNA polymerase II; positive regulation of cell population proliferation; positive regulation of DNA-templated transcription; positive regulation of double-strand break repair; positive regulation of transcription by RNA polymerase II; regulation of cell cycle; regulation of mitotic cell cycle; regulation of Ras protein signal transduction; regulation of reactive oxygen species metabolic process; regulation of DNA-templated transcription
Cellular component: nucleolus; nucleoplasm; chromatin; nucleus; RNA polymerase II transcription regulator complex; cytoplasm
Genetic constraint (gnomAD): Loss-of-function variants: 26 observed, 66.14 expected, observed/expected ratio (o/e) 0.39, 90% interval 0.29 to 0.55. The upper end of that interval is the gene's LOEUF score, 0.55, which puts it in group 2 of 6, group 1 being the genes least tolerant of losing a copy. Missense variants: 879 observed, 982.65 expected, observed/expected ratio (o/e) 0.89, 90% interval 0.85 to 0.95. Synonymous variants: 387 observed, 386.92 expected, observed/expected ratio (o/e) 1, 90% interval 0.92 to 1.09.
Homologues: Orthologues: chimpanzee FOXM1 (96% identical), macaque FOXM1 (95% identical), dog FOXM1 (84% identical), rabbit FOXM1 (83% identical), pig FOXM1 (82% identical), rat Foxm1 (82% identical), guinea pig FOXM1 (81% identical), mouse Foxm1 (80% identical), tropical clawed frog foxm1 (40% identical), zebrafish foxm1 (38% identical). Paralogues in human: FOXQ1 (14% identical), FOXO1 (12% identical), FOXO3 (12% identical), FOXJ3 (12% identical), FOXD1 (11% identical), FOXK1 (11% identical), FOXC1 (11% identical), FOXK2 (11% identical), FOXC2 (11% identical), FOXD2 (11% identical), FOXJ2 (11% identical), FOXN1 (10% identical), and 29 more.
Diseases named in the same sentence as FOXM1 in open-access papers:
FOXM1 is named in the same sentence as 320 diseases in open-access papers, as found by Europe PMC text mining. Sharing a sentence is not in itself a finding about the gene and the disease. The quoted sentences say what the papers report.
breast cancer (432 papers, 2008 to 2026). A primary or metastatic malignant neoplasm involving the breast. "Functional enrichment analysis confirmed that the target genes of FOXM1 were directly involved in the mitotic cell cycle-associated functions and revealed an activated proliferation of cycling myeloid cells in breast cancer." (PMID 41584858, 2026). "We found the ERG motif to be highly enriched alongside FOXM1, an oncogenic TF known to be highly upregulated in breast cancer and associated with poor patient survival, which was significantly enriched in accessible regions." (PMID 40946111, 2025). "For example, in breast cancer, overexpression of FOXM1 has been shown to be linked with tumor progression, while its downregulation is associated with an increase in metastasis." (PMID 39858603, 2025). "Overexpression of the FOXM1 gene has been identified in several types of cancer, including breast cancer, in association with advanced tumor stage, high proliferation, tumor aneuploidy, poor survival, shorter relapse free-survival, and chemoresistance." (PMID 40862714, 2025). "FOXM1 is overexpressed in a number of cancers, including breast cancer, and is associated with aggressive disease and poor prognosis." (PMID 40713647, 2025). "The overexpression of FOXM1 in many cancers including breast cancer is associated with advanced tumor stage, higher proliferation, and poor prognosis." (PMID 40002266, 2025). "Studies have shown that higher levels of HER2 are associated with increased expression of FOXM1 in both breast carcinoma cell lines and patient samples." (PMID 40002266, 2025). "FOXM1 is overexpression of in TNBC breast cancer and associated with tumor aggressiveness, metastasis, poor patient outcomes, and reduced overall survival rates." (PMID 38918225, 2024). "Following transcription factor enrichment analysis, we identified FOXM1 as a key transcription factor significantly associated with immune cell infiltration in breast cancer." (PMID 39834541, 2024). "In HER2+ breast cancers, FOXM1 has emerged as a key diagnostic marker and a critical downstream target of HER2 signaling." (PMID 39594778, 2024). "Recent studies have also shown that FOXM1 dysregulation is associated with cancer progression and the development of drug resistance in breast cancer." (PMID 39594778, 2024). "FOXM1 encodes an oncogenic transcription factor that plays a crucial role in carcinogenesis, notably in breast cancer." (PMID 39090361, 2024). "FOXM1 is highly expressed in different types of breast cancer and is associated with poor prognosis and chemotherapy resistance." (PMID 38697979, 2024). "Elevated levels of FOXM1 expression have been associated with an unfavorable prognosis in breast cancer, esophageal adenocarcinoma, and CRC." (PMID 39272919, 2024). "FoxM1 as an oncogenic transcription factor was associated with poor survival in breast cancer patients and can be used as a potential biomarker for targeted therapies and prognosis assessment in breast cancer patients." (PMID 38886335, 2024). "Discussion: High FOXM1 expression has been associated with radio and chemoresistance contributing to poor patient survival in multiple cancers, including breast cancer." (PMID 37025658, 2023). "In agreement with this, the overexpression of FOXM1 forkhead box is associated with a reduced mortality rate for breast cancer patients and can augment the tolerance of breast cancer cells to the medicine paclitaxel." (PMID 37626655, 2023). "High expression of FOXM1 in breast cancer is associated with larger tumor size, lymphovascular invasion, lymph node metastasis, aggressive phenotype, resistance to chemotherapy, and an overall poor prognosis." (PMID 37025658, 2023). "We found that higher expression of FOXM1 was associated with poor overall survival for ER+ breast cancers, which are mainly luminal tumors, from a large (n = 627) patient cohort." (PMID 36795481, 2023).
breast cancer (continued). "In most human cancers especially in breast cancer, FOXM1 protein is overexpressed, which can cause resistance to chemotherapy." (PMID 37736517, 2023). "Consonant with these observations, siRNA knockdown or pharmacological inhibition of FOXM1 abrogated all of the effects associated with cancer-driving FOXM1 activity, validating FOXM1 as a promising target for suppression of different breast cancers." (PMID 37370117, 2023). "Immunohistochemistry staining of tumors from 501 ERα-positive breast cancer patients revealed that high FOXM1 protein was associated with significantly decreased patient survival." (PMID 37370117, 2023). "The higher expression of FOXM1 is linked to lower patient survival, while the overproduction of the FOXM1 gene transcript is prevalent in breast cancer." (PMID 37626655, 2023). "In MCF-7 breast carcinoma xenografts, compound 3a (25 mg/kg every second day for 6 days, i.p.)inhibited tumor growth associated with induction of p21 and suppression of FoxM1 and survivin." (PMID 36835501, 2023). "The results demonstrated overexpression of FOXM1 partly reversed the decrease in breast cancer cells proliferation caused by knockdown of WDR5." (PMID 35524313, 2022). "It is noteworthy that overexpression of FOXM1 has been described to be strongly associated with lymph node metastasis in breast cancer and hence supports our analysis." (PMID 36318267, 2022). "The forkhead-box-protein M1 (FOXM1) is a transcriptional regulator whose expression is associated with resistance to endocrine therapies in ER+ breast cancers and metastatic progression." (PMID 33920089, 2021). "To determine the role of FOXM1 in luminal A breast cancer cells, we examined its loss-of-function phenotype in MCF7 and T47D cells with short hairpin RNA (shRNA)-mediated gene silencing." (PMID 34425866, 2021). "In brief, the altered expression pattern of FOXM1/GATA3/FOXA1/ESR1-associated lncRNAs in breast cancer suggests future assessment of the functional role of these genes in the development of breast neoplasms." (PMID 34094972, 2021). "Since FOXM1 is upregulated and overexpressed in aggressive therapy-resistant forms of breast cancer and is associated with worse prognosis of patients, Api warrants further study as a potential treatment for endocrine-resistant BC." (PMID 33466512, 2021). "For example, a proteomics study of the breast cancer cell line MCF-7 revealed that FOXM1 altered the expression of 37 proteins associated with mitochondrial biogenesis and glycolysis." (PMID 34205406, 2021). "KIF20A has been reported to be implicated in FOXM1-related chemoresistance in hepatocellular carcinoma and breast cancer." (PMID 33292277, 2020). "FOXM1 directly activates genes implicated in multiple phases of metastasis, and has been reported as the master regulator of metastasis in breast cancer, pancreatic cancer, melanoma and hepatocellular carcinoma." (PMID 33291076, 2020). "Several DUBs have been reported for FOXM1 regulation and their expression has been associated with cancer progression, including glioblastoma and breast cancers." (PMID 33142744, 2020). "Based on FOXM1 gene expression in the primary tumor, risk of relapse is increased in ER+ breast cancer compared with ER− breast cancer." (PMID 32976773, 2020). "Immunohistochemistry on 134 estrogen receptor (ER+) primary breast cancer samples confirmed that high eIF4E expression was significantly associated with increased ERα and FOXM1, and significantly associated with tamoxifen resistance." (PMID 32066877, 2020). "The risk-of-recurrence calculated from follow-up data from METABRIC, based on FOXM1 gene expression in the primary tumor, showed that the risk of relapse is increased in ER+ breast cancer compared with ER− breast cancer." (PMID 32976773, 2020). "FOXM1 has been found to directly regulate the transcription of Survivin and the X-linked inhibitor of apoptosis protein in breast cancer cells, providing good support to our findings." (PMID 31796105, 2019).
breast cancer (continued). "The underlying mechanism of action of FOXM1 in breast cancer involves sustained activation of SMAD3/SMAD4 activity, which further induces TGF-β-dependent EMT and promotes metastasis." (PMID 31554904, 2019). "Here, we discover FOXM1 as a novel molecular partner of HMGA1 in regulating a gene network implicated in several breast cancer hallmarks." (PMID 31311575, 2019). "Recent studies have confirmed that abnormal expression of FoxM1 is highly associated with the generation and progression of various human malignancies including breast cancer, liver cancer, lung cancer, and bladder cancer." (PMID 29554906, 2018). "In the current study, the antitumor mechanism of Moracin D, a constituent of Morus alba, was examined in breast cancer cells in association with FOXM1 and β-Catenin/GSK3β signaling." (PMID 30201862, 2018). "Consistently, in breast cancer patients with ER+ve tumours, low FOXM1 expression is associated with better survival." (PMID 29180117, 2018). "The aim of this study is to determine the expression level of FoxM1 in Middle Eastern breast cancer and to examine its association with clinico-pathologic variables as well as to assess its utility as a prognostic indicator." (PMID 29707121, 2018). "Overexpression of OTUB1 and upregulation of FOXM1 expression are associated with enhanced proliferative rate and epirubicin resistance in breast cancer." (PMID 29180117, 2018). "To illustrate the use of NFP, below we show an example on FOXM1 pathway in breast cancer that consists of transcriptional cancer drivers and risk genes." (PMID 28280740, 2017). "We examined the ability of using target genes to infer FOXM1 activity in tumor samples and investigated their association with patient survival in breast cancer." (PMID 29100329, 2017). "As a proliferation-associated transcription factor, FoxM1 plays pivotal roles in the development of various types of human malignancies, such as glioma, lung cancer, hepatocellular carcinoma, breast cancer, and pancreatic cancer." (PMID 28148279, 2017). "Expression of FOXM1 was associated with larger tumor size, lymphovascular invasion, lymph nodes metastases, and higher stage of breast cancer." (PMID 26942015, 2016). "The forkhead transcription factor FOXM1 has a key role in DNA damage response, and its deregulated overexpression is associated with genotoxic drug resistance in breast cancer." (PMID 26148240, 2016). "Microarray analysis of breast cancers demonstrates that FOXM1 regulates genes essential for chromosomal segregation and mitosis with loss of FOXM1 leading to mitotic spindle defects and mitotic catastrophe." (PMID 27074562, 2016). "FoxM1 plays a critical role in cancer metabolism, as the reduction of O-GlcNAc levels and OGT in cancer cells is associated with a decrease in protein expression of FoxM1 in breast cancer." (PMID 27703839, 2016). "To determine the in vivo function of FoxM1 in tumorigenesis of breast cancer cells, we performed FoxM1 loss-of-function studies by injecting 4T1-shFoxM1 and MDA-MB-231-shFoxM1 cells into the mammary fat pads of nude mice." (PMID 25869208, 2015). "Like the PDGF/AKT signaling pathway, which is also aberrantly activated in breast cancer, FoxM1 has been implicated in breast tumorigenesis." (PMID 25869208, 2015). "Our findings demonstrated that casticin repressed the expression of FOXM1 in breast cancer cells, which was associated with the downregulation of FOXM1 activity, revealed by the concomitant decrease in expression of its downstream target, survivin." (PMID 24765206, 2014). "Of interest, analysis of our microarray gene expression data from a large study with TAM-treated breast cancer patients showed that high FOXM1 mRNA expression in tumors was associated with a less good patient survival." (PMID 25213081, 2014). "FOXM1 (forkhead box protein M1) is a transcription factor and has been shown to associate with cisplatin-resistance and DNA damage response in breast cancer." (PMID 25051366, 2014).